CCL2 (C-C motif chemokine ligand 2)
Diseases named in the same sentence as CCL2 in open-access papers (continued):
Sharing a sentence is not in itself a finding about the gene and the disease.
tumor (continued). "IL-1β and TGF-β have crucial roles in CCL2-induced macrophage polarization and tumor-entrained neutrophil education, which weaken cytotoxic capacity and are also correlated with inflammation-induced immunosuppression." (PMID 34386431, 2021). "Monocyte infiltration toward tumor-derived fibroblast spheroids was high and considerable amounts of CCL2 were secreted by fibroblast spheroids." (PMID 34681633, 2021). "Some measures have been examined in this regard, including the CCL2 blocking that reduces monocyte recruitment and macrophage infiltration which leads to tumor growth inhibition." (PMID 34281293, 2021). "Chemokines, such as C–X–C motif chemokine ligand 8 (CXCL8) or C–C motif chemokine ligand 2 (CCL2) secreted by tumor cells also promote the accumulation of immunosuppressive cells at the tumor site." (PMID 34220833, 2021). "The ascites from the obese cKO mice showed increased vacuole clumps but decreased the floating tumor burden, tumor-attached macrophages, triglyceride, free fatty acid, CCL2, and TNF levels compared to obese WT mice." (PMID 34638514, 2021). "In the present study, we showed that CHI3L1 can tune the tumor microenvironment by liberating HS-bound molecules such as CCL2 or VEGF-A." (PMID 33920100, 2021). "An example of a potent chemokine in the attraction of monocytes to tumor sites is monocyte chemoattractant protein-1 (MCP-1, also known as CCL2)." (PMID 33451116, 2021). "For example, Qian BZ showed that CCL2-CCR2 mediated macrophage infiltration contributes to the distant metastasis of breast cancer, and high CCL2 expression in the tumor predicts poor prognosis in patients." (PMID 34580284, 2021). "The TAMs also stabilize and constitutively express HIF-1α under hypoxic conditions that facilitates the recruitment of macrophages to hypoxic regions of the tumor via the secretion of chemokines, such as CCL2 and endothelins (ETs)." (PMID 33230600, 2021). "IDO expression on tumor cells and CCL-2 secretion from microglia and macrophages in the tumor microenvironment contribute to recruiting Tregs (CD4+CD25+ FOXP3+)." (PMID 34421912, 2021). "For example, CCL2, expressed by cancer and stromal cells in the tumor microenvironment, induces tumor cell proliferation at the primary tumor site and stimulates tumor cell migration and invasion into the surrounding extracellular matrix." (PMID 34744703, 2021). "CXCL12, which led to PI3K and ERK1/2 activation in tumour cells, and CCL2, which was released by stromal cells and tumour cells to recruit myeloid cells, exhibited significantly increased expression in the exhausted groups than in the active groups." (PMID 34059019, 2021). "M2 type macrophages closely resemble tumor-associated macrophages (TAMs) and are characterized by increased expression of IFN-γ, CCL2, CCL5, CXCL16, CXCL10, CXCL9, TNF-α, MMP9 and IL-10, arginase-1, and peroxisome proliferator-activated receptor-γ (PPAR-γ)." (PMID 33925575, 2021). "TAMs constitute one of the most abundant populations of PDAC, and can derive from the differentiation of monocytes recruited by tumor-produced CCL2 and CCL5, or from embryonic precursors." (PMID 33802061, 2021). "In HCC, tumor-infiltrating Tregs are recruited to the neoplastic site following enhanced secretion of the chemokines CCL17 and CCL2 by tumor associated macrophages." (PMID 33953725, 2021). "In preclinical models, inhibition of PGE2 production through COX2 inhibitors, specifically acetylsalicylic acid and celecoxib, led to both the suppression of gliomagenesis and reduction of MDSCs in the tumor microenvironment through a decrease in CCL2." (PMID 34976006, 2021). "In various cancers, the activation of the CCL2/CCR2 axis, that mediates the crosstalk between TAMs and tumor cells, was associated with metastases and cancer progression." (PMID 34830817, 2021).
tumor (continued). "FAP+CAFs were the main source of CCL2, which facilitated the recruitment of myeloid-derived suppressor cells (MDSCs) to the tumor and promoted immunosuppression in a CCR2 dependent manner." (PMID 34336660, 2021). "NLRP7 protein levels were increased by USP10-mediated deubiquitination in CRC cells, which induced the polarization of pro-tumor M2-like macrophages via NF-κB pathway-mediated CCL2 secretion." (PMID 33838681, 2021). "Tumor cells have also been found to express CCL2, and multiple transcription factors overexpressed by cancer cell have been identified to affect CCL2 transcription." (PMID 34386431, 2021). "CCL2 can also recruit various immune cells (such as myeloid‐derived suppressor cells, MDSCs) to form an immunosuppressive microenvironment, which allows tumour cell to evade the body's immune surveillance and supports tumour cell proliferation." (PMID 34464477, 2021). "The analysis indicated that EE facilitated the reduction of CCL2 expression in Hepa1-6 tumor tissue with consistency." (PMID 34593796, 2021). "Via the release of CCL2, TAMs recruit further myeloid populations to the tumor, and through the released factors IL-10 and TGF-β, mitigate induction of immunosuppressive MDSC and suppression of APC recruitment and function." (PMID 33917501, 2021). "Following treatment with radiotherapy or chemotherapy, PDAC tumor cells release inflammatory molecules including the chemokine CCL2, which recruits inflammatory macrophages to promote tumor proliferation and vascularization." (PMID 34201127, 2021). "Macrophages and microglia within the murine GBM tumor microenvironment produce CCL2 cytokine to recruit CCR4+ Tregs and CCR2+ Ly6C+ myeloid cells." (PMID 34421912, 2021). "This study challenges the use of CCL2 as a monotherapy and highlights the need to understand the tumor microenvironment composition for successful anti-metastatic therapy." (PMID 33968034, 2021). "Pro-inflammatory cytokines, such as CXCL1/2/3/12 and CCL2 are produced by CAFs in the tumor microenvironment." (PMID 34901003, 2021). "In CRC mouse models, incomplete radiofrequency ablation(iRFA) induces sustained infiltration of MDSCs in residual tumors through tumor cell-derived CCL2, which inhibits T-cell function and hinders the efficacy of anti-PD-1 therapy." (PMID 35003065, 2021). "To conclude, CCL2 has both anti-tumor and pro-tumor effects, depending on the interaction between cancer cells and host cells." (PMID 34386431, 2021). "A preclinical study in hepatocellular carcinoma assessing the blockade of CCL2/CCR2 with the CCR2 antagonist RDC018 revealed hindered tumor growth and metastasis, reduced postsurgical recurrence, and prolonged survival." (PMID 34575965, 2021). "Monocytes/macrophages are actively recruited by tumor cells that produce chemokines such as CSF-1, monocyte chemoattractant protein-1 (MCP-1/CCL2), and CCL5." (PMID 34572013, 2021). "Whereas the use of an anti-CCL2 monoclonal antibody reduced both the growth of primary malignant lesions and the metastases number in an implantable tumor model, CCL2 or CCR2 knockout mice developed transgenic tumors and had an increased number of metastases." (PMID 33540898, 2021). "C-C motif chemokine ligand 2 (CCL2) induced various chemokine cascades in the stimulation of target-site tissues and tumor development by enhancing the retention of metastasis-associated immune cells." (PMID 34249913, 2021). "Blockade of CCL2 achieves tumour suppression through diverse ways such as blocking CCL2‐mediated signalling pathways, inhibiting the immunosuppressive cell recruitment and increasing the number of tumour‐killing cells." (PMID 34464477, 2021). "Next, we tested the effect of peripheral SNS on CCL2 expression in tumor sites using 6OHDA-induced sympathectomy." (PMID 34593796, 2021).
tumor (continued). "On the other hand, doxorubicin treatment can lead to CCL2 production by stromal cells from tumor microenvironment and contributes to drug resistance by recruitment of suppressive myeloid cells." (PMID 34804061, 2021). "Administration of CCL2 neutralizing antibodies reduced tumor growth, inhibited angiogenesis, and macrophage infiltration in a mouse model of clear cell renal cell carcinoma." (PMID 33919517, 2021). "Ccl2 is released by many cells present in the tumor microenvironment, including stromal cells, leukocytes, endothelial cells, and malignant cells, which results in augmentation of the plasma chemokine levels." (PMID 34504786, 2021). "CCL2 secreted by tumor cells can attract Th1 cells, Th17 cells and macrophages, which express high levels of CCR2, to the tumor site." (PMID 34683963, 2021). "The tumor cell-derived CCL2 transforms monocytes into M2-like macrophages, resulting in the increased production of EGF, which activates EGFR signaling in the tumor cells promoting the formation of invadopodia associated with increased HNSCC cell motility." (PMID 33925575, 2021). "Altogether, these data demonstrated the sympathetic modulation of tumor-derived and host CCL2 expression via β-ARs as a peripheral Neuro-Endocrine-Immune pathway for tumor regulation." (PMID 34593796, 2021). "Tumor-secreted factors, such as G-CSF, GM-CSF, CCL2, and VEGF, expand ERα-expressing myelocytic precursors in the bone marrow and recruit these immature cell populations to the cancer microenvironment." (PMID 34359625, 2021). "Tumor cells can generate monocyte chemoattractant protein-1 (CCL-2), also known as MCP-1, which is able to recruit monocytes and macrophages." (PMID 34834304, 2021). "It was consistent with our finding that both the tumor-derived and immune cells-derived CCL2 signaling were required for EE-induced antitumor immunity." (PMID 34593796, 2021). "A similar effect has been observed in animal models, where CCL2 suppressed tumor growth in a T lymphocyte-independent and/or -dependent manner." (PMID 33671869, 2021). "In various human neoplasia, higher levels of CCL2 are correlated with increased occurrence of metastasis and decreased overall survival." (PMID 34771482, 2021). "The activated Tregs are recruited into tumor by tumor-derived immunosuppressive cytokines IL-6 and CCL2 (P); for simplicity, we represent both cytokines by CCL2." (PMID 34061898, 2021). "Of note, CCR2 expression by tumor cells is also subject to regulation by its own ligands, as CCL2 has been shown to downregulate CCR2 in tumor cells." (PMID 34804061, 2021). "In line with this, reduced CCL2 expression in the tumor tissue was found in the DEN/CCl4-induced, CCl4-induced and DEN/HFD-induced HCC model under EE housing condition compared to SE." (PMID 34593796, 2021). "Classical chemotherapy and radiotherapy for cancer also stimulate CCL2-dependent chronic inflammation and tumor survival." (PMID 34386431, 2021). "In contrast, blockade of both tumor-derived and host-derived CCL2 signaling abolished the EE’s protective functions." (PMID 34593796, 2021). "Inflammatory mediators secreted by CAFs such as SDF-1, MCP-1/CCL2, IL-β, and RANTES/CCL5 induce immunosuppressive cells including myeloid-derived suppressor cells (MDSCs), regulatory T cells (Tregs), and tumor-associated macrophages (TAMs)." (PMID 34436224, 2021). "In turn, tumor-elaborated CCL2 paracrine signaling attracts CD11b+GR1+ myeloid cells to the pleural cavity." (PMID 33494181, 2021). "Their interaction with the BMDMs and tumor cells in the collagen-I matrix increased production of GM-CSF, G-CSF, IL-6, CCL2, CCL3, CCL4 and CCL12, and reduced production of IFN-β1, LIF, VEGF, CCL17, CXCL5 and CX3CL1." (PMID 34572807, 2021). "The CCL2 expression is correlated with TAMs recruitment to the tumor and subsequent tumor progression, with high expression resulting in high TAMs accumulation." (PMID 33230600, 2021).
tumor (continued). "The multiple tests allow to consider in the same model the association of the two variables (bacterium abundance and presence of tumor) to the CCL2 levels." (PMID 34639088, 2021). "CCL2 antibodies in combination with chemotherapeutic drug docetaxel also decreased tumour burden in prostate cancer." (PMID 33917287, 2021). "CCL2 is often overexpressed by tumor cells, and CCR2/CCL2 overexpression has been associated with worse outcomes in multiple malignancies." (PMID 33741032, 2021). "We have observed increased CCL2 secretion in all tumor cell lines co-cultured with chemotherapy-educated MSC (except for MDA + PAC-MSC) but marked difference was apparent mainly after co-culture with MSC exposed to DOX." (PMID 34579743, 2021). "Given that environmental eustress specifically reduced CCL2 levels and activated β-ARs signaling in the tumor microenvironment and given the essences of two signaling in EE-mediated tumor control, we decided to focus on the relevance of these signaling." (PMID 34593796, 2021). "The inhibition of Ido1 resulted in a T cell-dependent anti-tumor response in mice and CCL2 was involved in the recruitment of neutrophils, MDSCs, and monocytes into the TME, which was associated to tumorigenesis." (PMID 35126382, 2021). "Upregulation of CCL2 recruit macrophages to the tumor and passes VEGF- C promote lymphatic metastasis." (PMID 33391402, 2021). "Given the relevance of the USP12-mediated chemokine, such as CXCL8, CXCL1 and CCL2, in tumour development and progression, we examined the mechanism underlying the USP12-mediated regulation." (PMID 34381028, 2021). "For certain genes (Il10, Csf3, Cxcl1, Ccl2, Gata3, Il5, and Il13), there was a clear difference between the EC and HC Shb KO effects using Cdh5-CreERt2 or Vav1-Cre tumor-bearing mice, indicating that these effects reflect EC cell autonomy of Shb gene deletion." (PMID 34768912, 2021). "CCL2-mediated CCR2+ monocyte recruitment in the tumor was shown to significantly enhance the killing capacity of neutrophils." (PMID 34386431, 2021). "Consistantly, we found a U-shape relationship of NE/EPI concentration with CCL2 expression in cultured tumor cells, TAMs or MDSCs; that is, lower concentration of NE/EPI help to reduce the CCL2 expression, which higher concentration subverted this effect." (PMID 34593796, 2021). "CCL2 regulates the monocyte and macrophage migration and infiltration into inflamed, but also tumor tissues." (PMID 33540898, 2021). "In the tumor microenvironment, the interaction between CCL2 and C-C motif chemokine receptor 2 (CCR2) regulates the chemotaxis of TAMs and contributes to cancer progression." (PMID 33891564, 2021). "Synergic effects of parathyroid hormone derived from tumor cells and CCL2 derived from bone host cells contribute to bone remodeling and formation of a premetastatic environment." (PMID 34386431, 2021). "This has been further confirmed in CCL2 knockout mice in which metastasis of tumor cells was reduced." (PMID 34771552, 2021). "Several studies reported that CCL2 not only promotes tumor invasion and metastasis, but also acts as a macrophage recruiter and M2-stimulating factors." (PMID 33838681, 2021). "A novel mechanism of radiotherapy resistance was recently discovered wherein PDAC cells respond to radiotherapy-induced stress by releasing high levels of CCL2 that recruit inflammatory monocytes to promote tumor proliferation and vascularity." (PMID 34201127, 2021). "Neutralization of CCL2 prevents tumor cell migration, osteolysis, and angiogenesis in mouse models of bone-metastatic PrCa and BrCa." (PMID 34064859, 2021). "In concert with this, researchers found that the ratio of Th1/Th2 was prominently decreased within tumour tissues of high CCL2 expression." (PMID 34464477, 2021).
tumor (continued). "In brief, CCL2 promotes tumour angiogenesis by recruiting CCR2+ vascular endothelial cells and inflammatory cells and by stimulating the expression of angiogenic factors." (PMID 34464477, 2021). "Enhanced CCL2 release by irradiated tumor cells contributes to the recruitment of inflammatory monocytes and CCR2+ Tregs." (PMID 34386431, 2021). "MPM cells, by producing high levels of the monocyte chemoattractant protein CCL2, induced the recruitment of monocytes at tumor sites." (PMID 34830817, 2021). "In xenograft studies, CCL2-silenced M231-ADIR cells significantly attenuated tumor growth upon ADI treatment." (PMID 33664852, 2021). "These include blocking recruitment of TAM into the tumor by targeting chemokines such as CCL2 and CXCL12, which resulted in a reduction in tumor size." (PMID 34795675, 2021). "These myeloid cells are attracted from the circulation to the tumor site via chemokine pathways that tumor cells co-opt to enhance myeloid cell attraction like CCL2." (PMID 34957115, 2021). "CCL2, highly expressed in many types of cancers, can recruit monocyte and macrophages into tumors to promote tumor cell survival and contribute immune evasion." (PMID 34729117, 2021). "Substantial reductions in suppressive cytokines, including CCL2, CCL17, CCL22 and IL-10, were also noted and were associated with reduced CD4+ CD25+ Foxp3+ Treg recruitment in the tumour." (PMID 33513866, 2021). "Neutralization of CCL2 or CCR2 deficiency blocks monocyte recruitment, reduces MØs interacting with tumor cells and more importantly reduces lung metastasis." (PMID 34804061, 2021). "S100A8/A9 signal correlated with subsequent tumor burden of lung metastasis and selective CCL2 blockade was able to modulate TAM activity within the TME and influence subsequent metastatic growth." (PMID 33918295, 2021). "The stroma, as well as the tumor itself, are responsible for attracting these cells at the metastatic site by expressing CCL2." (PMID 33922795, 2021). "In the TME with low oxygen concentration, tumor cells can recruit TAMs by secreting more chemokines such as CCL2, CCL5, or CSF1." (PMID 34717710, 2021). "In HCC, TAM recruitment and activation depends, among other things, on tumor cell expression of glypican-3 and several chemokines, including CCL2 and M-CSF." (PMID 34831182, 2021). "The combination of anti-CCL2 Ab with docetaxel was shown to generate a more effective tumor regression than either Ab- or docetaxel-treatment alone." (PMID 33540898, 2021). "Arginine the down-regulation of enzyme 1 and CCL2 can reverse the function of tumor TAMs to anti-tumor phenotype 98." (PMID 33391402, 2021). "In a PDAC mouse model, tumor cells-derived CCL2 inhibited the efficacy of ablative radiotherapy by recruiting inflammatory monocytes/macrophages into the TME to accelerate tumor proliferation and angiogenesis." (PMID 34095111, 2021). "It is therefore reasonable to assume that the estrogen deprivation-elicited inhibition of ERβ signaling prevents the role of mast cells in promoting tumor invasion by decreasing CCL-2 expression." (PMID 33413549, 2021). "Other cytokines (CCL2, IFNγ, IL-12, IL-10, TNFα, IL-4, and IL-1β) evaluated were not significantly changed, suggesting that additional unidentified tumor-derived soluble factors promote alternative activation in BMDMs." (PMID 35008514, 2021). "TAMs can directly promote the proliferation of tumor cells by secreting growth factors and inflammatory mediators such as CCL2, IL-1α, IL-6, and TNF-α (step 3)." (PMID 33968034, 2021). "We found that CCL2, the dominant chemokine for the migration of tumor-promoting MDSC and regulatory T cells, was expressed in macrophage-1 and macrophage-2 subsets." (PMID 34671197, 2021). "At breast cancer, the release of CCL2 by tumor cells recruits inflammatory monocytes that polarize to metastasis-associated macrophages, which secrete CCL3, promoting lung metastasis." (PMID 34447383, 2021).